NBN (nibrin)
Diseases named in the same sentence as NBN in open-access papers (continued):
Sharing a sentence is not in itself a finding about the gene and the disease.
head and neck cancer (1 paper, 2014). A primary or metastatic malignant neoplasm affecting the head and neck. "Multivariate analysis for CAT and NBN polymorphisms with radiation-induced oral mucositis in presence of alcohol among head and neck cancer patients." (PMID 24594932, 2014). "In conclusion, we report that gene variants and haplotypes of NBN are associated with the risk of developing oral mucositis in head and neck cancer patients undergoing chemoradiotherapy/radiotherapy." (PMID 24594932, 2014).
Hodgkins lymphoma (1 paper, 2021). A heterogeneous group of malignant lymphoid neoplasms of B-cell origin characterized histologically by the presence of Hodgkin and Reed-Sternberg (HRS) cells in the vast majority of cases. "ALL and Hodgkin lymphoma share susceptibility to ATM and NBN mutations." (PMID 34117277, 2021).
Hyperglycemia (1 paper, 2024). An increased concentration of glucose in the blood.
Infertility (1 paper, 2023). "All female NBS patients are infertile (data are limited for males) and germline variants in NBN should be considered as a rare cause of infertility." (PMID 36982687, 2023).
Insulin resistance (1 paper, 2024). Increased resistance towards insulin, that is, diminished effectiveness of insulin in reducing blood glucose levels. "Interestingly, studies have shown that NBN directly interacts with JNK1 and plays a major role in insulin resistance." (PMID 39459569, 2024).
laryngeal carcinoma (1 paper, 2013). Carcinoma that arises from the laryngeal epithelium. "We have previously shown that the p.I171V NBN gene mutation may contribute to the development of laryngeal cancer." (PMID 24079363, 2013). "We have previously shown that the heterozygous p.I171V mutation of the NBN gene may contribute to laryngeal cancer (OR=11.7, 95% CI 1.3–105.2) and multiple primary tumors (OR=28.35, 95% CI 3.27–245.7)." (PMID 24079363, 2013).
leiomyosarcoma (1 paper, 2020). An uncommon, aggressive malignant smooth muscle neoplasm, usually occurring in post-menopausal women. "The immunohistochemistry staining analysis of CDK4, MYC, NBN, and DAXX in uterine leiomyoma (10 cases), LPD (4 cases), and leiomyosarcoma (10 cases) was subsequently conducted." (PMID 32359372, 2020). "LPD showed CDK4, NBN, DAXX, MYC moderately, and strongly positive, and uterine leiomyosarcoma displayed strongly positive." (PMID 32359372, 2020).
LIG4 syndrome (1 paper, 2022). LIG4 syndrome is a hereditary disorder associated with impaired DNA double-strand break repair mechanisms and characterized by microcephaly, unusual facial features, growth and developmental delay, skin anomalies, and pancytopenia, which is associated with combined immunodeficiency (CID). "Interestingly, impairment of DNA ligase IV (LIG4), nibrin (NBS1), or aprataxin (APTX) activity as a result of genes’ deleterious mutation leads to severe disorders in DNA damage response known as LIG4 syndrome, Nijmegen breakage syndrome (NBS), and Ataxia oculomotor apraxia-1." (PMID 36340042, 2022).
lung squamous cell carcinomas (1 paper, 2015). "Missense point mutations in an extended analysis of ATM, MRE11A, RAD50 and NBN are present in 16/212 lung squamous cell carcinomas (7 %) are present in the TCGA database." (PMID 26438152, 2015).
lymphoid tumour (1 paper, 2016). "Nevertheless, the presence of a lymphoid tumour in both affected individuals does raise the interesting possibility that PALB2 may represent a novel tumour suppressor of lymphoid malignancies in a manner similar to ATM and NBN." (PMID 26990772, 2016).
oral mucositis (1 paper, 2014). Inflammation of the mucous membranes of any of the structures in the mouth. "Haplotype analysis of NBN (rs1805787, rs1805794) gene demonstrated G-C haplotype to be associated with development of oral mucositis (odds ratio of 1.687 and 95% CI of 1.005–2.831 with p = 0.047)." (PMID 24594932, 2014). "In continuation, multivariate analysis indicated that odds of patients experiencing severe oral mucositis (grade >2) with recessive allele of NBN (rs1805794) was 4.72 times higher having a confidence interval of 1.384–16.151 and p = 0.013." (PMID 24594932, 2014). "However, it indicated that odds of patients experiencing severe oral mucositis (grade >2) with recessive allele of NBN (rs1805794) was 3.75 times higher having a confidence interval of 1.201–11.70 and p = 0.023." (PMID 24594932, 2014).
cancer (121 papers, 2009 to 2026). A tumor composed of atypical neoplastic, often pleomorphic cells that invade other tissues. "Several individual genetic association studies, including meta-analyses, have investigated the association of two SNPs (rs1805794 and rs709816) of NBN gene with multiple cancer risks." (PMID 41797823, 2026). "The impact of NBN heterozygous pathogenic variants on cancer risk continues to be a moving target with a recent study in adults suggesting these carriers to exhibit a potential pan-cancer risk." (PMID 40925926, 2025). "Although there are a growing number of NBN variants detected in cancer patients, efforts to assess their association with B-ALL predisposition are limited." (PMID 37503171, 2023). "A second germline variant was found in PALB2, CHEK2, ATM, and NBN, and they presented an additional cancer at the ages of 37, 57, 52, and 58, respectively." (PMID 36003761, 2022). "NBN rs1805794 has been suggested to interfere with the interaction properties of Nibrin and thus with DNA repair capacity, sensitivity to DNA damaging agents (such as IR) and cancer susceptibility." (PMID 32957448, 2020). "Here we identify mutation hotspots in MRE11, RAD50, NBS1/NBN, and CtIP from analyzed cancer data on COSMIC." (PMID 33339169, 2020). "Accordingly, NBN rs1805794 has been repeatedly associated with cancer risk, as demonstrated by numerous meta-analysis but conflicting reports exist." (PMID 32957448, 2020). "Six pathogenic variants (in BRCA1,BMPR1A,FANCA,FANCC,NBN genes) with cancer related phenotype and three unsolicited variants (in BRCA2,PALB2,RAD50 genes) were reported to patients." (PMID 31937788, 2020). "NBN overexpression also appears to be associated with poor prognosis in several types of cancer, which is consistent with a putative increase in DNA repair efficiency, hence, resistance to cytotoxic therapy." (PMID 32957448, 2020). "Genetic variants in the NBN gene have been associated with multiple cancers risk, suggesting pleiotropic effect on cancer." (PMID 26402912, 2015). "NBN p.Arg215Trp was of interest because association studies have found evidence that it confers modest risk of several cancers, and there is biochemical evidence, albeit somewhat conflicting, of altered function of this nibrin allele." (PMID 24894818, 2014). "More importantly, individuals carrying biallelic hypomorphic NBN mutations suffer from the Nijmegen breakage syndrome, being susceptible to several types of cancer." (PMID 23586058, 2013). "The NBN polymorphisms, especially p.E185Q, have been investigated in some cancer but results were inconclusive." (PMID 24093751, 2013). "For example, heterozygous carriers of deleterious mutations in the NBN gene, in particular the Slavic founder mutation 657del5, has been associated with a 2- to 3-fold increased risk of cancer." (PMID 19523210, 2009). "NBN-deficient cells display elevated levels of baseline DNA damage, chromosomal instability, and aberrant cell cycle control, which is considered to drive cancer development." (PMID 37503171, 2023). "Representative studies analyzing associations of germline NBN variants with cancer risk." (PMID 36982687, 2023). "In addition, mutations within the BRCT domain tandem of nibrin (NBN) were associated with an increase susceptibility to cancer development." (PMID 36361992, 2022). "Additionally, pathogenic alterations in PALB2, ATM, CHEK2, and NBN are correlated with an increased risk for breast cancer and/or other cancers, whereas other genes such as BRIP1, RAD51C, and RAD51D are associated with an increased ovarian cancer risk." (PMID 32733558, 2020). "In some areas of the world, the NBN gene became the most important cancer-predisposing gene." (PMID 32564008, 2020).
cancer (continued). "Overall, despite extensively investigated, the functional significance of NBN rs1805794, as well as its putative role in sensitivity to DNA damaging agents (such as IR) and cancer susceptibility remains elusive, warranting further studies to clarify this issue." (PMID 32957448, 2020). "Additionally, ~6% of women (20/333) were carriers of the pathogenic or likely pathogenic variants in other cancer-related genes, with NBN and CHEK2 reported as the most frequently mutated, accounting for 1.8% (6/333) and 1.2% (4/333) of cases, respectively." (PMID 30441849, 2018). "The two patients who did not meet the Jongmans’ criteria carried monoallelic PSVs in BLM and NBN, genes associated with autosomal recessive cancer predisposition syndromes, and a single heterozygous variant is generally insufficient to confer a clinically meaningful cancer risk." (PMID 40779059, 2025). "However, such deficiency may occur by somatic inactivation and much larger case–control association studies will be needed to finally resolve the role of NBN germline variants in the etiology of this cancer." (PMID 37013556, 2023). "NBN c.657_661del (p.Lys219Asnfs*16), an Eastern European founder loss-of-function frameshift variant associated with increased risk for breast, prostate, colorectal, and additional cancers, was identified in three siblings in branch 10, who were unaffected by cancer at the close of study." (PMID 36612224, 2022). "Moreover, NBN was the most frequently altered gene with four identified carriers of a recurrent Slavic c.657del5 variant that moderately increases the risk of various cancer types in our population." (PMID 36612198, 2022). "Likewise, in our next studies we found that specific haplotypes of the NBN gene may be associated with the same cancer patients." (PMID 24079363, 2013). "However the impact of other NBN variants on cancer risk is unclear." (PMID 19523210, 2009). "Of these, 103 patients (8.6% of the total sample) carried germline pathogenic variants in genes that have been definitively linked to an increased risk of PC or other types of cancers (BRCA2, ATM, CHEK2, NBN, BRCA1, PALB2, BRIP1 and BARD1)." (PMID 41465280, 2025). "Approximately 10% of patients with aggressive PC carry germline pathogenic variants in genes with established roles in cancer predisposition (BRCA2, ATM, CHEK2, NBN, BRCA1, PALB2, BRIP1, BARD1)." (PMID 41465280, 2025). "In the non‐cancer cohort, 25/492 (5%) participants carried 17 unique P/LP variants in ATM, BRCA2, BRIP1, CHEK2, MUTYH, NBN, and PMS2 genes." (PMID 38308423, 2024). "Here, we show that cancer manifestation of NBN homozygotes is at a later age in probands from Poland than from CS." (PMID 36806726, 2023). "The analysis of 10,489 tumors performed by Wu and colleagues revealed that NBN amplification was the most prominent DDR gene event that occurred in over 40% of patients across 16 cancer types." (PMID 36982687, 2023). "Here, we show that cancer manifestation of NBN homozygotes is at a significantly earlier age in probands from CS than from Poland." (PMID 36806726, 2023). "PARPi activity was also demonstrated for BRCAwt cancers due to mutations in genes critical for DNA repair (e.g., ATM, BARD1, BRIP1, CHEK2, NBN, PALB2, RAD51C, and RAD51D)." (PMID 36910637, 2023). "We have found that the most altered cancer-related genes include NBN, RAD51C, BRIP1 (mostly with amplification events), and CDH1 (usually with losses or deep deletions)." (PMID 37239898, 2023). "The most altered cancer-related genes include NBN, RAD51C, BRIP1 (mostly with amplification events), and CDH1 (usually with losses or deep deletions)." (PMID 37239898, 2023). "PV were detected in 13 cancer predisposition genes including ATM (n=4), BLM (n=1), BRCA1 (n=1), BRCA2 (n=7), BRIP1 (n=1), CDKN2A (n=1), CHEK2 (n=9), FANCC (n=1), MUTYH (n=10), NBN (n=1), PALB2 (n=1), RAD51D (n=1) and STK11 (n=1)." (PMID 36091166, 2022).
cancer (continued). "Of the patients, 73.2% underwent genetic testing, and 30% of them presented germline likely pathogenic or pathogenic variants in cancer predisposition genes (24 BRCA1, 4 BRCA2, 1 PALB2, 1 NBN, and 1 ATM)." (PMID 36531080, 2022). "In line, the truncating, heterozygous c.(657del5) NBN variant in Case-32 has been described as the Slavic founder variant occurring in >90% of NBS patients, and heterozygous carriers have an elevated cancer risk." (PMID 33840814, 2021). "The most frequently amplified genes across the Pan-Cancer Atlas were NBN (n = 4,275, 40.8%), EXO1 (n = 3,714, 35.4%), PARP1 (n = 3,695, 35.2%), PRKDC (n = 3,650, 34.8%) and POLB (n = 2,794, 26.6%)." (PMID 32226530, 2020). "Altogether, these in vitro experiments are consistent with both the proposed function of nibrin in telomere protection and with the occurrence of cancer forms with high ALT prevalence in NBS." (PMID 32564008, 2020). "Consistently, NBN depletion significantly sensitized these cancer cells to cisplatin or olaparib treatment." (PMID 32226530, 2020). "Mutations in HR genes can cause genome instability and predisposition to cancer; for example, ataxia telangiectasia, Nijmegen breakage syndrome, and Bloom syndrome are caused by mutations in ATM, NBN, and BLM, respectively, and are associated with pleiotropic cancer susceptibility." (PMID 39870965, 2025). "The NBN gene is reported to be a contributor to a broad cancer spectrum and may have contributed to the multiple cancers in our patient’s family." (PMID 40243416, 2025). "Among the younger group, 53 had BRCA1/2 germline PVs/LPVs (38%), 15 were carriers of other cancer susceptibility genes (10%), primarily APC, NBN, ATM, MUTYH, MLH1, and only 2 patients were carriers of PVs/LPVs in both BRCA1/2 and other susceptibility genes (1%)." (PMID 38136276, 2023). "Taken together, our results highlight the importance of germline pathogenic NBN variants to B-ALL predisposition, which may inform clinical strategies and cancer surveillance in these children in the future." (PMID 37503171, 2023). "Extended genetic screening revealed additional germline variants within the cancer-associated NBN, MC1R, and PTPRJ genes in non-LS branches of the family in which several members also had cancer diagnoses." (PMID 36612224, 2022). "According to the local testing criteria in use, 73.2% of patients included in this study underwent genetic testing, and 30% of them presented germline likely pathogenic or pathogenic variants in cancer predisposition genes (24 BRCA1, 4 BRCA2, 1 PALB2, 1 NBN, and 1 ATM)." (PMID 36531080, 2022). "We propose this scenario as an underlying genetic mechanism in the siblings studied herein (Case-77/Case-78) in whom we detected VUSs in the DNA repair genes NBN and RAD51C, which might jointly lead to cancer susceptibility." (PMID 33840814, 2021). "In addition, as many as 4% of these individuals have germline pathogenic mutations in cancer predisposition genes other than BRCA1 and BRCA2 on MGPT (i.e. CHEK2, PALB2, ATM, NBN, PTEN, etc.)." (PMID 33541411, 2021).